KDM3B (lysine demethylase 3B)
Diseases named in the same sentence as KDM3B in open-access papers (continued):
Sharing a sentence is not in itself a finding about the gene and the disease.
cancer (16 papers, 2012 to 2025). A tumor composed of atypical neoplastic, often pleomorphic cells that invade other tissues. "Taken together, these data provide strong evidence that KDM3B is a childhood cancer predisposition gene." (PMID 30885698, 2019). "Large-scale, broad mutation testing of FBXW7 and KDM3B in individuals with cancer will probably be required to establish the full spectrum of associated cancers, because of the rarity of truncating variants and the challenges in interpreting non-synonymous variation in these genes." (PMID 30885698, 2019). "KDM3B also appears to be a pleiotropic cancer predisposition gene." (PMID 30885698, 2019). "Finally, we identified two de-novo KDM3B mutations, supporting the role of KDM3B as a childhood cancer predisposition gene." (PMID 30885698, 2019). "Simultaneous knockdown of KDM3A and KDM3B reduced the tumorigenic potential of cancer stem-like cells in CRC cells through regulation of the Wnt/β-catenin pathway." (PMID 38926399, 2024). "Another study reported that high KDM3B expression in breast cancer cells and tissues leads to rapid growth and invasion of cancer cells." (PMID 39239542, 2024). "Several studies have reported the physiological roles of KDM3B in different type of cells, including those from cancers and leukemia." (PMID 32716961, 2020). "Therefore, small molecule targeting of KDM3B can resensitize Erastin‐resistant cancer cells to ferroptosis induction and thus may have potential as a possible strategy to induce ferroptosis‐associated cancer cell death." (PMID 32107878, 2020). "We show that wild-type KDM3A and KDM3B are H3K9me1/2 demethylases, report absence of enzymatic activity of JMJD1C and establish Suppressor of cancer cell invasion (SCAI) as a novel interaction partner of KDM3B." (PMID 23593242, 2013). "Also, KDM3B inhibitors are undergoing intensive investigation for their potential application in cancer treatment, including BC." (PMID 41046340, 2025). "Our data suggests that KDM3B is a critical regulator of autophagy in cancer." (PMID 32716961, 2020). "However, the molecular mechanisms underlying the role of KDM3B in regulating cancers have not been well elucidated till date." (PMID 32716961, 2020). "Secondly, KDM3B and KDM3C have been found to function with fusion oncogenes that occur only in certain cancers." (PMID 38926399, 2024). "KDM3B and KDM3C show context-dependent functions, showing pro- or anti-tumorigenic abilities in different cancers." (PMID 38926399, 2024). "In conclusion, P3FI-90 inhibits multiple KDMs with highest selectivity for KDM3B that can be further developed for the therapy of highly malignant FP-RMS and possibly other “transcriptionally addicted” cancers." (PMID 38402212, 2024). "Many unresolved questions surrounding the mechanisms of KDM3B and KDM3C in tumorigenesis remain to be disclosed, leaving hope for further pharmacological opportunities to fight cancer using epigenetic therapy." (PMID 38926399, 2024). "While a predominant number of research reports on the significant role of KDM3A in various cancers, an increasing number of studies imply aberrant activities of KDM3B and KDM3C and their deregulation in a variety of cancers." (PMID 38926399, 2024). "We observed that KDM3B is significantly expressed in RMS cell lines, having the second highest levels of KDM3B expression overall compared to other cancer lines, indicating that it is a potential target for therapy." (PMID 38402212, 2024). "KDM3A and KDM3B are well known to be tightly related to cancer, whereas KDM3C and KDM4D are relatively unstudied in cancer development." (PMID 32354028, 2020). "Lastly, deeper understanding of the cellular context-dependent roles of KDM3B and KDM3C in various cancers may provide novel insights on targeting KDM3B and KDM3C in cancer therapy." (PMID 38926399, 2024). "Distinctive functions KDM3B and KDM3C play in tumorigenesis could be explained by cancer-specific expression of their epigenetic target genes." (PMID 38926399, 2024).
cancer (continued). "Although much is studied about the roles of KDM3A in cancers compared to those of KDM3B and KDM3C, the latter two lysine demethylases are not to be overlooked." (PMID 38926399, 2024). "An online database analysis (TIMER 2.0) shows the differential expression patterns of KDM3A and KDM3B (KDM3C not available) in various cancers and adjacent normal tissues across all TCGA tumors, highlighting their importance in tumorigenesis." (PMID 38926399, 2024). "Thus, this review provides a thorough understanding of the involvement of KDM3B and KDMC in oncology that should be helpful in determining the role of KDM3 proteins in preclinical studies for development of novel pharmacological methods to overcome cancer." (PMID 38926399, 2024). "Hence this review specifically addresses the roles of KDM3B and KDM3C in cancers." (PMID 38926399, 2024).
KDM3B also shares sentences with these, for which no sentence is quoted: breast carcinoma (4 papers); acute promyelocytic leukemia (2); hepatoblastoma (2); hepatocellular carcinoma (2); Hodgkins lymphoma (2); myeloid leukemia (2); ovarian carcinoma (2); prostate carcinoma (2); anemia (1); autism spectrum disorder (1); breast tumors (1); childhood kidney tumor (1); cognitive disorder (1); epilepsy (1); glioblastoma (1); granulocytosis (1); Hip dysplasia (1); interstitial lung disease (1); leukocytosis (1); lymphoma (1); male infertility (1); non-small cell lung carcinoma (1); osteosarcoma (1); pancreatic cancer (1); Parkinson’s (1); schizophrenia (1); small cell lung carcinoma (1); Witteveen-Kolk syndrome (1).